ALK (ALK receptor tyrosine kinase)
Diseases named in the same sentence as ALK in open-access papers (continued):
Sharing a sentence is not in itself a finding about the gene and the disease.
lung cancer (continued). "Indeed we have observed in case reports that non-responding metastatic do not have molecular expression of the primary site (EGFR, ALK, ROS1, ALK or PD-L1) or there are cases where we have a different lung cancer or lung cancer transformation 34-36." (PMID 31598145, 2019). "Although the ALK G689R nutation is labeled as a variant of undetermined significance (VUS) at present, alterations in ALK gene are involved in many malignancies including lung cancer and could mediate acquired resistance to some ALK inhibitor." (PMID 30755180, 2019). "Moreover, ceritinib, which is approved for anaplastic lymphoma kinase (ALK) positive lung cancer, can also inhibit IGF1R and INSR." (PMID 31480400, 2019). "The initiation of lung cancer is caused by a number of factors, including genetic alterations such as mutations in K-Ras, epidermal growth factor receptor (EGFR), anaplastic lymphoma kinase (ALK), phosphoinositide 3-kinase (PI3K), and BRAF." (PMID 30987652, 2019). "Interplay has been reported between EGFR, STAT3, and ALK in lung cancers." (PMID 30634502, 2019). "Anaplastic lymphoma kinase (ALK) is a receptor tyrosine kinase that has been recognized as a therapeutic target for EML4-ALK fusion-positive nonsmall cell lung cancer (NSCLC) treatment using type I kinase inhibitors such as crizotinib to take over the ATP binding site." (PMID 31388026, 2019). "While NSCLC patients with EGFR and ALK mutations show relatively improved survival compared with those with wild-type EGFR and ALK22,23, determining the prognostic value of the PLR in wild-type EGFR and ALK lung cancer would be meaningful." (PMID 30886226, 2019). "In addition, ALK rearranged lung adenocarcinomas were more frequently pT1 tumors compared with ALK-non rearranged lung cancer." (PMID 30744664, 2019). "In our study, CTC characterization analysis demonstrated that ALK-rearrangement status in NanoVelcro captured CTCs showed reliable consistency with that in the tumor specimen, and ALK-rearrangement was consistently detected in CTC from lung cancer patients harboring this rearrangement." (PMID 30658713, 2019). "In summary, we reported an autopsy case of ALK-positive lung cancer that worsened in a short time." (PMID 31030664, 2019). "Second, the results from this study are relevant to ALK-translocated lung cancer." (PMID 30658414, 2019). "With CTCs capture and their corresponding ALK detection, dynamic monitoring of treatment effect for lung cancer patients could be realized during the process of Crizotinib treatment." (PMID 30658713, 2019). "This lower genetic complexity of ALK-driven NSCLC compared to other lung tumors may explain why therapeutic progress has been much faster and survival gains much larger for ALK+ compared to other lung cancer patients." (PMID 31139322, 2019). "Three DEGs (DHFR, GART and ALK) also played roles as anti-lung cancer drugs target genes." (PMID 30642283, 2019). "Next, we tested four lung cancer tissue specimens harboring ALK fusion, EGFR mutation, KRAS mutation, or none." (PMID 30943926, 2019). "Rearrangement of the anaplastic lymphoma kinase (ALK) gene defines a distinct clinicopathologic subset of non‐small cell lung cancer (NSCLC) and occurs in approximately 3–7% of NSCLC cases, with a higher prevalence among younger, never/light smoker, and adenocarcinoma histology." (PMID 31633304, 2019). "Ceritinib is approved for ALK-positive lung cancer and can also inhibit IGF1R." (PMID 31234291, 2019). "Surgical resection of recurrent or persistent tumour after effective systemic treatments seems important for survival and might produce TFR and/or a cure, especially in a highly selected subgroup of ALK‐positive lung cancer patients." (PMID 31285825, 2019). "For instance, a lung cancer patient with no ALK or ROS translocations and EGFR mutations and with a relatively low expression of PD-L1 and a medium to high neoantigen load would be eligible for the adjuvant NCV approach." (PMID 29678194, 2018).
lung cancer (continued). "Additionally, one recent study showed reactivation of the RAS-MAPK pathway as a novel mechanism of acquired resistance in ALK-positive lung cancers." (PMID 29973561, 2018). "In general, failure to achieve tumor growth inhibition by crizotinib could be due to mutations in the ALK kinase domain that effect inhibitor binding or increase ALK catalytic activity or ALK gene amplification both observed in therapy-resistant lung cancer." (PMID 29755689, 2018). "In the first study, 347 patients who presented with ALK-positive lung cancer and had previously received a platinum-based chemotherapy treatment regimen were randomly assigned to receive either oral crizotinib or intravenous chemotherapy with pemetrexed or docetaxel." (PMID 29455675, 2018). "Immunohistochemically, ALK-rearranged lung cancers show cytoplasmic ALK staining." (PMID 29538329, 2018). "Furthermore, in subgroup analysis of international clinical phase III trial (PROFILE1007) aimed at Anaplastic lymphoma kinase (ALK) positive advanced lung cancer, pemetrexed showed higher effect than docetaxel." (PMID 29291705, 2018). "Ideally in vitro functional assays need to be adapted to any type of molecular alteration including gene amplifications (known to be driver alterations such as ERBB2 in breast cancer), translocations (such as ALK in lung cancer), and deletions of tumor suppressor genes (such as PTEN)." (PMID 29464843, 2018). "Molecular targeted therapies such as tyrosine kinase inhibitors (TKIs) in epidermal growth factor receptor (EGFR) mutants and anaplastic lymphoma kinase (ALK) inhibitors in ALK rearranged NSCLC patients have recently advanced the management of lung cancer for a limited proportion of patients." (PMID 30155443, 2018). "Anaplastic lymphoma kinase (ALK) inhibitors, such as crizotinib, alectinib, and ceritinib, are currently developed and are among the treatment options for ALK rearrangement-positive lung cancer, which accounts for 3%–5% of all cases of NSCLC." (PMID 29854794, 2018). "This study also demonstrates that a combination of both ALK and the RAS-MAPK component MEK inhibitors could be a potential approach to overcome resistance and improve the prognosis of ALK-positive lung cancer." (PMID 29973561, 2018). "In a recent study, using next generation sequencing analysis in a patient-derived ALK-translocated lung cancer cell line after ceritinib treatment, a MAP2K1-K57N activating mutation was found as the primary genetic alteration which was leading to MEK activation." (PMID 29495603, 2018). "A higher prevalence of ALK rearrangement may be attributed to the presence of advanced disease stages among lung cancer patients who are diagnosed via cytology specimens." (PMID 30572846, 2018). "In the absence of an intelligent way to guide the therapeutic sequence and on the basis of the availability of ALKis, this retrospective analysis may give a real picture of the outcome of ALK positive lung cancer patients." (PMID 29632648, 2018). "This review summarizes the hot topics of immunohistochemistry in lung cancer, including (i) adenocarcinoma vs squamous cell carcinoma; (ii) neuroendocrine markers; (iii) ALK, ROS1, and EGFR; (iv) PD-L1 (CD274); (v) lung carcinoma vs malignant mesothelioma; and (vi) NUT carcinoma." (PMID 29538329, 2018). "Therefore, we sought to investigate the effects of combined radiotherapy and ALK-inhibition via TAE684 in ALK-positive vs. wild type lung cancer cells." (PMID 29304828, 2018). "In lung cancer patients, ALK gene amplification, mutation, and rearrangement is known to be associated with tumor development, and around 5% of NSCLC cases are diagnosed with an ALK gene rearrangement." (PMID 29973561, 2018). "In addition to ECH, SQSTM1-ALK has also been reported in some cases of ALK-positive large B-cell lymphoma and lung cancer." (PMID 29747676, 2018).
lung cancer (continued). "However, drug resistance is a major limiting factor, and the prognosis of patients with ALK-positive lung cancer is still less-than-optimal." (PMID 29455675, 2018). "In this study, we aimed to discover novel therapeutic targets to conquer ALK-positive lung cancer." (PMID 29930762, 2018). "In this study of 33 patients who received continued crizotinib therapy after RECIST-defined disease progression, the ORR and initial PFS time (PFS1) were consistent with those reported in phase 1-3 clinical trials of crizotinb monotherapy in patients with ALK-positive lung cancer." (PMID 28427213, 2017). "Although most patients with ALK-positive non?small-cell lung cancer (NSCLC) who benefit from treatment with crizotinib ultimately develop progressive disease (PD), continuing crizotinb beyond the initial PD (CBPD) in these patients may be beneficial." (PMID 28427213, 2017). "Second, unlike other vaccine strategies that target dispensable tumor antigens, ALK positive lung cancers appear to be dependent on ALK signaling for cell survival, and genomic ALK rearrangements persist even after acquired resistance to ALK inhibitors emerges." (PMID 29190913, 2017). "Alternatively, the differential rate of acquiring or eliminating EGFR, ALK, or ROS1 lung cancer somatic mutations may be also influenced by the inheritance of the EGLN1D4E/C127S variant which modulates HIFs-stability." (PMID 28036300, 2017). "For instance, somatic mutations in EGFR and translocation of ALK (both genes known to affect lung cancers) occur at higher rates in nonsmoking lung cancer patients than in the tumors of smoking lung cancer patients." (PMID 28106732, 2017). "We intended to determine whether the ALK translocations of primary lung cancers are consistent with those in corresponding metastatic lymph node tumors." (PMID 29312572, 2017). "For all specimens from enrolled lung cancer patients, ALK was first scored using IHC." (PMID 29118432, 2017). "Furthermore, crizotinib is a kinase inhibitor for multiple lung cancer oncogene including ALK, c-Met, and ROS1, especially for ROS1-rearranged NSCLC." (PMID 28615068, 2017). "Although a previous study showed that ALK-positive lung cancers have unique biologic features with early nodal metastasis despite a small-sized primary tumor (pT1, P = 0.02), we found that ALK IHC-positive lung adenocarcinoma is associated with a higher tumor stage (pT4, P = 0.025)." (PMID 29156778, 2017). "In this study we investigated whether IGF-1R is an independent druggable target in ALK-positive lung cancer cells." (PMID 29066738, 2017). "The authors also proposed that the efficacy of ceritinib against crizotinib resistant lung cancer might be partially explained by its dual IGF-1R/ALK inhibitory action." (PMID 29066738, 2017). "Approximately 3–7% of lung cancer patients harbor ALK fusions." (PMID 27791985, 2017). "ALK-rearranged lung cancers exhibit specific clinical and pathologic features." (PMID 28549458, 2017). "Importantly, co-targeting EGFR (in lung cancer) or ALK (in NB) and the molecules that drive these pathways can reverse TKIs resistance." (PMID 29143801, 2017). "Neoantigen-based vaccines could provide an alternative therapeutic option to treat refractory ALK+ cancers such as lung cancer." (PMID 29189709, 2017). "Additionally, the real-time PCR method developed by AmoyDx was recently approved in China to detect ALK hybrids in lung cancer patients." (PMID 28032602, 2017). "Our results also support the hypothesis that ALK and IGF-1R are independent druggable targets in ALK-positive lung cancer." (PMID 29066738, 2017). "Prompt and correct ALK test results may save time and effort later on for many advanced and/or recurrent lung cancer patients." (PMID 29118432, 2017).
lung cancer (continued). "Given a higher objective response rate of anti-PD-1 and anti-CTLA-4 in PD-L1 positive lung cancer, it is reasonable to consider adding anti-PD-1 and/or anti-PD-L1 antibodies to the treatment of ALK+ lung cancer, particularly at the time of resistance to ALK inhibitor monotherapy." (PMID 29189709, 2017). "Crizotinib is superior to standard first-line pemetrexed plus platinum chemotherapy in patients with previously untreated, advanced ALK rearrangement-positive NSCLC, which is associated with a greater reduction in lung cancer symptoms and a significant improvement in quality of life." (PMID 28032602, 2017). "While several fusion genes involving ALK produced by chromosomal rearrangements have been found in a subset of lymphomas and lung carcinomas, recently, deregulated expression of full-length ALK has also been observed in some primary solid tumors derived from various tissues." (PMID 28193280, 2017). "A systematic review of pharmacological interventions performed on GEMMs of lung cancer suggest that with respect to the most clinically relevant mutations, such as those in EGFR and ALK, GEMMs well recapitulated the features of human tumours in terms of response and resistance mechanisms." (PMID 27350784, 2016). "Finally, with so many promising second- generation inhibitors in early trials, we can expect that the prognosis for patients with all ALK mutant tumours, not only lung cancer, will keep improving." (PMID 27350784, 2016). "Another reasonably common mutation identified in two landmark studies in 2007 was the first somatic oncogenic gene translocation in lung cancer, involving fusion of two genes, EML4 (echinoderm microtubule associated protein-like 4) and ALK (anaplastic lymphoma kinase)." (PMID 26755435, 2016). "Ceritinib, discussed here, certainly has dramatic activity against ALK positive lung cancer." (PMID 27480287, 2016). "Patients harbouring ALK translocations have a prognosis generally considered severe compared to that of its wild type counterpart; however, confounding data have emerged from the literature about the prognostic role of ALK translocation in lung cancers." (PMID 27433281, 2016). "ALK-specific tyrosine kinase inhibitors (TKIs) have become important new drugs for ALK-driven lung cancer, but acquired resistance via multiple mechanisms including kinase-domain mutations eventually develops, limiting median progression-free survival to less than a year." (PMID 27009859, 2016). "Moreover, high levels of AXL are involved in crizotinib (ALK inhibitor) resistance in lung cancer patients and contribute to FLT3 inhibitor resistance in acute myeloid leukemia (AML)." (PMID 27590506, 2016). "Although ALK inhibition and autophagy have not been extensively studied until now our findings, and those from Ji and colleagues in lung cancer, suggest that ALK inhibition might provoke autophagy-dependent resistance." (PMID 27486382, 2016). "The inhibition of ALK is another successful example of molecular therapy in lung cancer." (PMID 27350784, 2016). "Additionally, the National Comprehensive Cancer Network (NCCN) guideline (Version 1.2015) suggested crizotinib should be chose as first-line treatment for any performance status of ALK positive lung cancer." (PMID 27835601, 2016). "However, EGFR and ALK aberrations collectively account for only approximately 15% of all NSCLCs in the US, and the overall survival rate for lung cancer patients remains extremely poor (5-year survival rate of ~15%)." (PMID 27705911, 2016). "Similarly to our analysis, some other studies evaluating the incidence and potential prognostic implications of ALK gene aberrations have been performed in lung cancer with debatable results." (PMID 27561692, 2016). "Thus, our test is an easily implementable diagnostic tool for the rapid, efficacious and cost-effective screening of ALK status in patients with lung cancer." (PMID 27206799, 2016).
lung cancer (continued). "In addition, by targeting exons 27–28 in the 3′ portion of ALK, our assay is able to detect also the recently identified ALK isoforms (though rare in lung cancer), encompassing exons 20–29." (PMID 27206799, 2016). "Therefore, it is mandatory to clarify the role and mechanism of this genetic aberration in order to identify and validate effective therapeutic approaches in this subpopulation of lung cancer patients harboring ALK-CNG." (PMID 27561692, 2016). "Whether this higher expression identifies a small fraction of lung cancers sensitive to ALK inhibitors remains to be established." (PMID 27206799, 2016). "Moreover, clonal selection of ALK-rearranged CTCs during crizotinib therapy was detected in patients with lung cancer." (PMID 26980749, 2016). "Over the last decade, the development of targeted therapy has prompted efforts to genetically classify patients with lung carcinomas into subsets, such as epidermal growth factor receptor (EGFR)-mutated type, and anaplastic lymphoma receptor tyrosine kinase (ALK)-rearranged type." (PMID 27648828, 2016). "Break-apart ALK FISH probe is the FDA approved approach for detection of ALK rearrangements in lung carcinoma patients who may benefit from ALK kinase inhibitors." (PMID 27769042, 2016). "ALK inhibitors exhibit marked anti-tumour activity against lung cancers with ALK rearrangements." (PMID 26373952, 2015). "The echinoderm microtubule-associated protein-like 4 - anaplastic lymphoma kinase gene (EML4-ALK) fusion oncoprotein, which arises from an inversion within chromosome 2p and results in constitutive kinase activity by dimerization of ALK, represents a major molecular target in lung cancer." (PMID 26219569, 2015). "Crizotinib is a key drug in the current therapeutic strategy for ALK-positive lung cancer." (PMID 25941796, 2015). "Although, ALK-rearranged lung cancer accounts for only 3-7 % of NSCLC since its discovery in 2007, this population could represent more than 70,000 new cases worldwide annually." (PMID 26219569, 2015). "The histomorphology of ALK-rearranged lung cancer cannot be used as a screening method." (PMID 26253541, 2015). "Crizotinib could be an effective method for ALK-positive lung cancer with bone marrow metastasis and showed good tolerance." (PMID 25676401, 2015). "Clarification of the resistance mechanisms relevant to ALK-positive lung cancer may be important to find ways to overcome drug resistance." (PMID 26219569, 2015). "In the literature, ALK-rearranged lung cancers make up only 3–7% of all NSCLC cases." (PMID 26575266, 2015). "In addition, heat shock protein (HSP) 90 inhibitors are suggested as therapeutic options to overcome resistance on the basis of anti-tumor activity in preclinical models of ALK-driven lung cancer and small-scale clinical trials on ALK-positive lung cancers." (PMID 26219569, 2015). "In summary, the induction of P-gp expression may contribute to the acquired resistance to 17-DMAG in lung cancer cells with an ALK rearrangement." (PMID 26219569, 2015). "Although an important step in pancreatic cancer, as in EGFR- or ALK-mutant lung cancer or BRAF-mutant melanoma might include investigation of matched targeted monotherapy, many pancreatic tumors likely contain more than one aberration." (PMID 25714017, 2015). "The recent advances in genomics have proved to be linked to prognosis and response to therapy, for instance BRAF inhibitors have changed the landscape of BRAF V600 E mutant melanomas, and ALK inhibitors have dramatically changed the outcome of EML4-ALK mutant lung cancer patients." (PMID 25859559, 2015). "The Vysis LSI ALK Break Apart FISH Probe Kit (Abbott Molecular, Des, Plaines, IL) has become a Food and Drug Administration (FDA)-approved companion diagnostic agent to the ALK inhibitor, crizotinib, in a targeted therapy for lung cancers." (PMID 25785456, 2015). "In lung cancer, crizotinib has shown clinical benefits in patients with ALK rearrangements." (PMID 26678488, 2015).